CD4 (CD4 molecule)
Diseases named in the same sentence as CD4 in open-access papers (continued):
Sharing a sentence is not in itself a finding about the gene and the disease.
Pleural effusion (50 papers, 2008 to 2026). The presence of an excessive amount of fluid in the pleural cavity. "Thus, the diagnostic accuracy of CD4+IL-9+ frequency in pleural effusion was 67.04% (59/88)." (PMID 34925358, 2021). "The χ 2 text and Mann-Whitney U Test analysis indicated that ESR, CD4+ T cells, NK cells, IL-4, duration of fever, and pleural effusion were significant predictors of NP in children with MPP (P < 0.05)." (PMID 41695751, 2026). "Analysis of DEGs in Cycling GZMA and GZMA CD4 T cells from pleural effusion of HP and LCP revealed that seven transcription factors (MLLT3, KLF12, FOXP1, NFKB1, ZEB2, TOX, JAZF1) were upregulated in both cycling GZMA CD4 and GZMA CD4 cells in MPE of LCP." (PMID 40959273, 2025). "By comparing Cycling GZMA CD4 and GZMA CD4 T cells in the pleural effusion between HP and LCP, we found that both the cytotoxicity score and GZMA expression were significantly reduced in the MPE of LCP." (PMID 40959273, 2025). "The proportion of T cells in pleural effusions was similar in patients with malignant or benign PE whereby CD4+ T cells were predominant in all patient groups." (PMID 39325190, 2024). "Treg plays a crucial role in regulating the immune response in pleural effusions by controlling the activity of CD4+ and CD8+T cells and their production of IFN-γ." (PMID 39003443, 2024). "Pleural effusions from lung cancer often show significantly elevated levels of CD4+T lymphocytes, which are the primary source of IL-10 production." (PMID 39003443, 2024). "The VEGF and pH of pleural effusion before treatment are independent poor prognostic factors, and the change in the ratio of CD4+/CD8+ in pleural effusion before and after treatment is an independent predictor of treatment efficacy." (PMID 35794989, 2022). "The results showed that VEGF and pH in pleural effusion before treatment were independent poor prognostic factors, and the trend of CD4+/CD8+ changes in pleural effusion before and after treatment was an independent predictor of treatment efficacy." (PMID 35794989, 2022). "The results of this study showed that patients with low VEGF expression, pleural effusion pH ≥ 7.35, and high CD4+/CD8+ ratio in pleural effusion were more effective in treatment and had a longer survival period." (PMID 35794989, 2022). "The results showed that patients with low expression of VEGF, pleural effusion pH ≥ 7.35, and high CD4+/CD8+ ratio in pleural effusion had a longer survival period and more effective treatment (–6)." (PMID 35794989, 2022). "In our study, we found IL-8 levels in patients with pleural effusion CD4/CD8 ratio < 1.93 were higher than those with ratio ≥ 1.93." (PMID 33931705, 2021). "Our study is also the first to use the CD4/CD8 ratio in pleural effusion to predict patient survival after ICI use." (PMID 33931705, 2021). "We identified those with CD4/CD8 ratios of pleural effusion ≥ 1.93 were well predicted for their survival." (PMID 33931705, 2021). "IL-8 levels in the pleural effusion of patients with CD4/CD8 ratios < 1.93 were higher than those with ratio ≥ 1.93." (PMID 33931705, 2021). "Sources of IL-27 in TB pleural effusions appear to be monocytes, MΦ, B cells, both CD4+ and CD8+ T cells, NK/NKT cells as well as mesothelial cells." (PMID 35116036, 2021). "Little is known about the impact of HIV and depletion of CD4+ T-cells on the pathogenesis of pleural TB, or the identity of the mycobacterial antigens persisting in TB pleural effusions." (PMID 32611401, 2020). "TRAPs isolated from tumor cell lines and pleural effusions or ascites of cancer patients were incubated with CD4+ T cells to examine the function and mechanism of TRAPs in CD4+ T cell differentiation and function." (PMID 31300052, 2019). "The level of expression was evaluated in CD4+CD25+ cells in relation to CD4+CD25− cells isolated from pleural effusions." (PMID 29785404, 2018).
Pleural effusion (continued). "Some heterogeneity was noted, including two patients with <3% CD4+CD25+ T cells and one patient with 21% CD4+CD25+ T cells in pleural effusion." (PMID 29601534, 2018). "Other less common findings, such as pleural effusion, which was also rare in our study (12.1% in the patients with low CD4+ T cell counts and 5.9% in the patients with normal CD4+ T cell counts, P = 0.64)." (PMID 29237413, 2017). "In conclusion, we report a case in which pleural sarcoidosis was diagnosed on the basis of lymphocytic predominance and an increased CD4/CD8 lymphocyte ratio in pleural effusion fluid obtained by thoracentesis." (PMID 26271927, 2015). "The lymphocytic predominance and the increased CD4/CD8 lymphocyte ratio were also detected in the right-sided pleural effusion fluid obtained by thoracentesis." (PMID 26271927, 2015). "Healthy subjects also had mainly CD8+ T cells in their pleural fluids, while patients with benign or malignant pleural effusion had mainly CD4+ T cells: the median pleural CD4+/CD8+ ratio in healthy subjects was 0.59 while in patients it always exceeded 2.2." (PMID 23816056, 2013). "We analyzed the association of cavities, consolidation, pleural effusion and hilar lymphadenopathy with time to sputum culture conversion, adjusting for HIV status, baseline sputum smear and CD4 count." (PMID 24040132, 2013). "Our group and other authors have reported that the CD8+ T-cell subpopulation in pleural effusion is reduced, while the CD4+ T-cell subpopulation is increased." (PMID 23118782, 2012). "Following, we validated the expression profiles of genes in the peripheral CD4+ T cells from each group and examined secretion levels of distinct cytokines in serum and pleural effusion." (PMID 22719887, 2012). "In most patients of types 1 and 2, their CD4/CD8 ratios ≥ 1.93 in pleural effusion." (PMID 33931705, 2021). "In conclusion, current data suggest that the determination of ADA, CD4+IL-9+, and Treg cells in pleural effusion may be an important diagnosis marker for TPE." (PMID 34925358, 2021). "Most patients of types 1 and 2 effusions possessed pleural effusion with CD4/CD8 ratios ≥ 1.93." (PMID 33931705, 2021). "In those patients presented with typical type 1 or type 2 pleural effusion but with CD4/CD8 ratios < 1.93, serial follow-up is recommended because elevating ratio may indicate a good response to ICI." (PMID 33931705, 2021). "Infiltration of inflammatory cells with CD4+ predominant may contribute to elevated CD4/CD8 ratio in the pleural effusion." (PMID 33931705, 2021). "CD4/CD8 ratio ≥ 1.93 in pleural effusion after ICI use is a good predicting factor in PFS." (PMID 33931705, 2021). "CD4/CD8 ratio ≥ 1.93 in pleural effusion is a good predicting factor for PFS." (PMID 33931705, 2021). "The median PFS of those with pleural effusion CD4/CD8 ≥ 1.93 and < 1.93 were 18.4 and 1.2 months." (PMID 33931705, 2021). "Three type 3 patients had initial pleural effusion CD4/CD8 ratios ≥ 1.93." (PMID 33931705, 2021). "Therefore, we analyzed the capacity of infDCs in pleural effusions from untreated NSCLC patients to induce autologous CD4+ T-cell differentiation." (PMID 32052078, 2020). "The correlation analysis included CD4+CD25+ cells from all collected pleural effusions." (PMID 29785404, 2018). "Analysis of the CD4/CD8 lymphocyte ratio in pleural effusion fluid obtained by thoracentesis may be helpful for the diagnosis of pleural sarcoidosis when the diagnosis is already made by histological examination of more than one organ specimen." (PMID 26271927, 2015). "Therefore we concluded that this was a case of pleural sarcoidosis with the elevation of CD4/CD8 lymphocyte ratio in pleural effusion." (PMID 26271927, 2015). "The increased CD4/CD8 lymphocyte ratios in BALF and pleural effusion fluid suggested that T-lymphocytes bearing CD4 are activated not only in the lungs but also in the pleura, which may be helpful for diagnosis of pleural sarcoidosis." (PMID 26271927, 2015).
Pleural effusion (continued). "Compared to pleural effusion in HP, the proportion of Cycling GZMA CD4 T cells significantly increased in MPE of LCP, whereas the proportion of GZMA CD4 T cells notably decreased." (PMID 40959273, 2025). "The measured lymphocyte populations (T, CD4+ and CD8+ T, NK, and Treg cells) in the pleural effusion fluid showed higher frequencies in the TPE group than in the PPE group." (PMID 38742106, 2024). "Using the Miltenyi CliniMACS Prodigy system, a GMP-compliant platform capable of cell selection and expansion in a closed system, we selected 1 x 108 CD4+ and CD8+ cells from a single NSCLC pleural effusion." (PMID 37063842, 2023). "The frequency of CD4+IL-9+, CD4+IL-17+, CD4+ IL-22+, and CD4+CD25+FOXP3+ cells in the pleural effusions." (PMID 34925358, 2021). "Our results also confirm the presence of CD4+ T cells, CD8+ T cells and macrophages in pleural effusions of MPM patients." (PMID 29163783, 2017). "Univariate analysis identified duration of fever, peak body temperature, pleural effusion, rash, WBC, N%, L%, PLT, LDH, CRP, CD3+ cells, CD3 + CD4+ cells, CD3 − CD19+ cells and CD19 + CD23+ cells as significant corticosteroid-resistant RMPP risk factors." (PMID 28008989, 2016). "The tumor volume was decreased and pleural effusion was reduced in patient #1823, who develop also positive DTH, CD4+ and CD8+ T cell responses." (PMID 25694811, 2014). "The lineage tracking in one study indicated that the CD4 + T- and CD8+ T-cell populations with distinct effector functions expanding at pleural sites and granzyme K-expressing CD8 T cells were preferentially enriched and clonally expanded in pleural effusion." (PMID 39664375, 2024). "The median OS for the group with pleural effusion CD4/CD8 ≥ 1.93 and < 1.93 were not reached and 2.6 months." (PMID 33931705, 2021). "In the non-disease progression group, 87.5% showed pleural effusion CD4/CD8 ratio ≥ 1.93, compared with 33.3% in the disease progression group (p = 0.036)." (PMID 33931705, 2021). "Patient no.17 developed pleural effusion 19 months after starting durvalumab medication, and CD4/CD8 and B cell ratios then increased, while cytological results were positive." (PMID 33931705, 2021). "Though the initial CD4/CD8 ratio of patient no.1 (type 1) was only 1.89, serial pleural effusion CD4/CD8 ratios examined showed progressively elevated ratios, with the highest reaching 13.8." (PMID 33931705, 2021). "For patients with adenovirus pneumonia, those without pleural effusion had significantly higher CD4+ T cell counts relative to those with pleural effusion." (PMID 33959573, 2021). "We present the case of a 51-year-old woman with HIV and CD4+ T helper lymphocytes cell count > 200 cells/ul on both ART and trimethoprim/sulfamethoxazole prophylaxis who presented with cavitating lung masses, mediastinal lymphadenopathy and pleural effusions." (PMID 34249178, 2021). "The aim of this study was to explore various mycobacterial antigens in pleural effusions, the impact of HIV infection and CD4+ T-cell depletion on the presence of antigens, and the diagnostic potential of antigens for improved and rapid diagnosis of pleural TB." (PMID 32611401, 2020). "Patients without pleural effusion had significantly higher counts of CD4+ (p = 0.034), CD8+ (p = 0.031), and CD20+ T cells (p < 0.004)." (PMID 28270104, 2017). "Compared to GZMA CD4 T cells in pleural effusion without tumors, those in MPE of LCP—whether non-proliferative or cycling GZMA CD4 T cells—exhibited suppressed cytotoxic function and reduced GZMA expression." (PMID 40959273, 2025). "The last correlation analysis included CD4+CD25+ cells from nonmalignant pleural effusions." (PMID 29785404, 2018). "Naïve Th cells (CD3+CD4+CD45RO-CD62L+) and naïve cytotoxic T cells (CD3+CD8+CD45RO-CD62L+) were slightly reduced in pleural effusion compared to peripheral blood (not significant)." (PMID 39737183, 2024).
Pleural effusion (continued). "The percentages of NK cells and CD20+ B lymphocytes, but not CD4+ T and CD8+ T lymphocytes, were different between LAC and HF pleural effusions." (PMID 30816121, 2019). "Patients without pleural effusion had significantly higher counts of CD4+, CD8+, and CD20+ T cells (all p < 0.05) compared to patients with pleural effusion." (PMID 28270104, 2017). "Accordingly, we recently reported that CD8+, but not CD4+, T-cells from malignant pleural effusions undergo AICD and this phenomenon is not observed in peripheral blood CD4+ and CD8+ T-cells." (PMID 23118782, 2012). "Patients with pleural effusion had significantly fewer leukocytes and T lymphocytes (CD4 +, CD8+, or CD20+) compared to patients without pleural effusion, suggesting that the presence of parapneumonic effusion in adenoviral pneumonia was a hallmark of depressed host cellular immunity." (PMID 28270104, 2017). "CD8+, CD4+, and CD4+/FoxP3+ T-cells are present in the majority of patients, but the number of T-reg cells in pleural effusions of MPM patients is lower than in other solid tumors, confirming the presence of an immunosuppressive milieu in MPM tumoral mass, rather than in pleural effusion." (PMID 34073720, 2021).
respiratory infections (50 papers, 2007 to 2025). "The additional diagnosis codes from CD4 to CD6 were excluded since these episodes could likely be due to other causes than respiratory infections and including them in the case definition might cause noise to the surveillance." (PMID 40843520, 2025). "Loss of RAMDs due to tissue repair correlated with a decline in CD8+ TRM number in mice, whilst in humans iBALT diminishes with age which may explain why older age groups are more susceptible to respiratory infection due to a reduced ability to mount CD4+ TRM/BRM responses." (PMID 34603321, 2021). "Our results demonstrate that CCR2 expression on naïve CD4+ T cells is initially low and significantly upregulated by day 7 p.i. following C. muridarum respiratory infection, although the expression remains at a relatively low level." (PMID 39903705, 2025). "This group also saw improvements in immune function indicators, such as IgA, IgG, IgM, and CD4+ levels, and a reduction in the number of respiratory infection episodes." (PMID 38892528, 2024). "Respiratory infections were rarer in adult heterozygous patients, who also showed normalization of CD4+ T cell levels." (PMID 33464451, 2021). "Further research should explore the impact of potential clinical modifiers on longitudinal lung function such as CD4 count, viral load, and previous significant respiratory infections including TB." (PMID 30897116, 2019). "In a mouse model of pneumonia, repeated respiratory infections with Streptococcus pneumoniae (pneumococcus) seeded the lungs with antibacterial CD4 TRM cells that mediated heterotypic protection." (PMID 30147701, 2018). "Recent studies demonstrated that respiratory infection with a number of different viruses can also induce CD4 TRM cells." (PMID 30147701, 2018). "The etiology of these respiratory infections varies according to factors such as CD4 levels, location of home, socioeconomic conditions and use of chemoprophylaxis." (PMID 27191248, 2016). "In response to infection, memory CD4 T cells that are protected from in vivo antibody labeling have been identified in lungs following respiratory infection with influenza virus, Mycobacterium tuberculosis (Mtb), and systemic infection with LCMV." (PMID 25071787, 2014). "Together, these findings indicate the importance of lung TRM in protecting against respiratory infections, suggesting that targeting generation of persisting CD4 TRM in the lung would provide optimal protection." (PMID 25071787, 2014). "The proportion of CD4 cases among all respiratory infections was 28% overall and ranged from 19% to 44% in participating hospitals (p < 0.01)." (PMID 22452874, 2012). "It would be useful to have a system in which memory CD4+ T cells established by respiratory infection are the only cross-reactive T cell subset, though such a system does not currently exist." (PMID 21647373, 2011). "Induction of IL-10+ CD8 T cells by CD4 T cell-derived IL-2 may thus act as further layer of buffering against damaging inflammation during respiratory infections." (PMID 31412088, 2019). "Very recently, it was shown that respiratory infection with Pneumocystis murina influences the alpha and beta diversity of the gut microbiota of CD4+ intact and CD4-depleted mice and resulted also in changes in taxa abundances indicating the role of a gut-lung axis during Pneumocystis infection." (PMID 29202739, 2017). "To assess the contribution of TGF-β on the anti-viral CD4 T cell response during a respiratory infection, we infected TGF-βRII WT and KO Stg chimeras i.n. with a recombinant influenza virus expressing the LCMV GP66–77 epitope recognized by the Stg TCR (WSN-GP33/66)." (PMID 25569154, 2015). "Most research to date has focused on CD8+ T-cells in the elderly and these observation strongly support a new line of research in the elderly to understand how and why skewing of the CD4+ T-cell compartment contributes significantly to the outcome of respiratory infection." (PMID 25275464, 2014).